NF1 (neurofibromin 1)
Diseases named in the same sentence as NF1 in open-access papers (continued):
Sharing a sentence is not in itself a finding about the gene and the disease.
lung adenocarcinoma (38 papers, 2014 to 2025). A carcinoma that arises from the lung and is characterized by the presence of malignant glandular epithelial cells. "NF1 mutations have been described in both lung adenocarcinomas and squamous cell carcinomas, at rates of 8.3% and 12%, respectively, with a lower prevalence in Asian populations." (PMID 41170454, 2025). "NF1 is recognized as a pivotal tumor suppressor, and its mutation can lead to a unique clinicopathologic subtype of lung adenocarcinoma." (PMID 40771813, 2025). "We showed that NF1-mutated lung adenocarcinomas are associated with a high TMB, high immune genes expression, and CD8 + T-cells infiltration." (PMID 38341500, 2024). "TMB was significantly higher in NF1-mutated versus NF1 wild-type (WT) lung adenocarcinoma (p < 0.0001) with a mean TMB at 14.1 mut/Mb [0.7–65.7] in NF1-mutated tumors versus 6.5 mut/Mb [0.0–96.5] in NF1 WT tumors." (PMID 38341500, 2024). "Little is known about immune checkpoint inhibitors (ICI) response of NF1-mutated lung adenocarcinomas." (PMID 38341500, 2024). "Additional studies are warranted to specify the biological effect of NF1 mutations on immune environment in lung adenocarcinoma." (PMID 38341500, 2024). "NF1 mutation status appears as a candidate predictive biomarker for ICI response in lung adenocarcinoma patients." (PMID 38341500, 2024). "We compared the mRNA levels of nine immune genes in NF1-mutated (N = 66; 9.6%) vs NF1 WT (N = 620; 90.4%) lung adenocarcinomas." (PMID 38341500, 2024). "Our results highlight the need for clinical trials evaluation ICI efficacy specifically dedicated to NF1-mutated lung adenocarcinomas with a randomization based on NF1 status." (PMID 38341500, 2024). "Since gain-of-function EGFR mutations tend to be mutually exclusive with loss-of-function SPRED1 and NF1 mutations in lung adenocarcinoma, we used oncogenic EGFR(L858R) as a model system." (PMID 32697994, 2020). "Our results confirm that NF1 is frequently mutated and represents a distinct molecular and clinical subtype of lung adenocarcinoma." (PMID 31199580, 2019). "In our series, NF1 mutations and deletions were found in 17.5% and 8% of lung adenocarcinoma surgical specimens, respectively." (PMID 31199580, 2019). "Corresponding with reported activity of NF1 as a tumor suppressor and negative regulator of RAS in lung adenocarcinomas, truncating mutations in NF1 tend to be mutual exclusive with activating mutations in RAS and BRAF (TCGA) in these tumors." (PMID 30858928, 2019). "Whole exome or genome sequencing of primary lung adenocarcinomas identified NF1 as one of the most frequently mutated genes, with an estimated frequency of 11-12%." (PMID 25026295, 2014). "341/4,181 (8.2%) TCGA lung adenocarcinomas samples have a somatic NF1 mutation." (PMID 38341500, 2024). "In 14 TCGA cohorts, 341 out of 4181 lung adenocarcinoma patients (8.2%) presented a NF1 mutation." (PMID 38341500, 2024). "In addition to neurofibromatosis type 1, the NF1 gene is often mutated in a variety of sporadic human malignancies, including glioblastoma, lung adenocarcinoma, acute myeloid leukemia, and ovarian and breast cancers." (PMID 32697994, 2020).
lung adenocarcinoma (continued). "In addition, previous study show that low expression of NF1 was associated with primary and acquired resistance of lung adenocarcinomas to EGFR‐TKIs in patients." (PMID 29493886, 2018). "Subgroup analyses revealed a potential association between NF1 mutations and improved ICI efficacy, in line with findings in lung adenocarcinoma." (PMID 40911493, 2025). "Somatic pathogenic mutations in NF1 are found in approximately 4.7%–10% of NSCLC, with a higher frequency in lung adenocarcinomas, reaching up to 15% in certain cohorts." (PMID 41170454, 2025). "In the context of lung adenocarcinomas, only two case reports showed durable responses to ICI in two patients with sporadic NF1-mutated cancers." (PMID 38341500, 2024). "NF1 mutations were associated with significantly higher CD8 + T cells (p = 0.03) and macrophage (p = 0.02) infiltrations in lung adenocarcinoma compared to NF1 WT tumors." (PMID 38341500, 2024). "A heatmap representing the mRNA expression z-score in 686 lung adenocarcinomas with available expression data (NF1 mutant: N = 66, 9.6%; NF1 WT: N = 620, 90.4%) is shown." (PMID 38341500, 2024). "Nf1 suppression increases Kras-driven lung adenocarcinoma and affects PSAT1-related glutamate dependency." (PMID 33526036, 2021). "Most driver alterations in lung adenocarcinomas, such as mutations in KRAS and EGFR, ALK fusions, and loss of NF1 function, confer activation of the Ras/Raf/ERK pathway." (PMID 32158759, 2020). "A study provided evidence to suggest that NF1 silencing decreased the sensitivity of erlotinib-induced cell apoptosis and/or growth arrest in lung adenocarcinoma cells." (PMID 33061844, 2020). "An appreciation of the functional role of NF1 gene dosage in lung adenocarcinoma development will be important for prediction of response to therapeutics." (PMID 31199580, 2019). "Our results are consistent with previous published data and confirm the implication of NF1 somatic alterations in lung adenocarcinoma with distinct molecular and clinical characteristics." (PMID 31199580, 2019). "Recently, a report showed that lower expression of NF1 was significantly correlated with primary and acquired resistance of lung adenocarcinomas to EGFR‐TKIs in patients." (PMID 29493886, 2018). "We did not have sufficient clinical outcomes of patients with NF1-mutated lung adenocarcinoma and treated with ICI in these TCGA public databases." (PMID 38341500, 2024). "We sought to investigate whether NF1 could be a predictive biomarker of response to ICI in a large cohort of lung adenocarcinoma." (PMID 38341500, 2024). "NF1‐mutant lung adenocarcinoma patients had inferior disease‐free survival (DFS), and overall survival (OS) compared to those with the EGFR-mutation, and downregulation of NF1 expression caused by truncating mutations was reported to confer resistance to EGFR-TKI in lung adenocarcinoma patients." (PMID 34195081, 2021). "So, FGL2 might affect NF1 function by influencing immune status in tumor environment of lung adenocarcinoma." (PMID 32206449, 2020). "The clinical significance of NF1 mutations in the lung adenocarcinoma sequencing studies is not reported, but reduced NF1 mRNA expression was recently found to confer both intrinsic and acquired resistance to EGFR inhibitors in another recently reported study." (PMID 25026295, 2014). "In lung adenocarcinomas, FAK1 is negatively regulated by NeuroFibromin 1 (NF1), leading to metabolic rewiring." (PMID 35348905, 2022).
soft tissue sarcoma (36 papers, 2007 to 2026). A malignant neoplasm arising from muscle tissue, adipose tissue, blood vessels, fibrous tissue, or other supportive tissues excluding the bones. "MPNSTs are aggressive soft-tissue sarcomas that are typically associated with NF1, while approximately 40% of MPNSTs arise sporadically after radiation exposure." (PMID 41179673, 2025). "GSK2126458 is expected to work in cells with altered PI3K signaling, and mutations in PIK3CA or NF1 have been shown to be some of the few mutations identified in soft tissue sarcomas." (PMID 33690666, 2021). "It accounts for approximately 5 to 10 % of all soft tissue sarcomas and has a strong association with NF-1, also known as von Recklinghausen’s neurofibromatosis." (PMID 26141125, 2015). "MPNSTs represent about 10% of all soft tissue sarcomas, and are associated with NF1 in 32 to 60% of cases." (PMID 24516522, 2014). "MPNSTs comprise almost 10% to 12% of all soft tissue sarcomas, which are primarily associated with NF1." (PMID 23198228, 2012). "In addition, somatic NF1 mutations, including deletions, have been reported in a wide variety of paediatric and adult soft-tissue sarcomas with complex karyotypes." (PMID 28061772, 2017). "This clearly suggested that cancer cell lines other than soft-tissue sarcoma carrying NF1 mutation/deletion may also show sensitivity to glutamine deprivation." (PMID 29212209, 2017). "MPNST represents 5-10% of all soft tissue sarcomas and is often associated with NF-1." (PMID 24507572, 2014). "The work also has direct implications for the role of the immune system and IFN signaling radiation-based treatment of soft tissue sarcomas beyond those involved in NF-1." (PMID 41766655, 2026). "A comprehensive genomic analysis has reported that the NF1 gene is one of the most frequently altered genes in soft tissue sarcomas (STS)." (PMID 38903727, 2024). "Abnormal activation of RAS by defective NF1 is a central driver event in some soft-tissue sarcomas (MPNST)." (PMID 33909629, 2021). "This type of tumors accounts for approximately 5–10% of all soft tissue sarcomas during adulthood whereas in more than 50% of these patients NF-1 also coexists." (PMID 25317349, 2014). "Any patient with an MPNST in association with NF1should be carefully staged prior to treatment and should be managed by amultidisciplinary team familiar with both soft tissue sarcomas and NF1." (PMID 19360115, 2009). "MPNST account for 10% of all soft tissue sarcomas with half of these malignancies arising in patients with NF1." (PMID 17997819, 2007). "MPNST is a rare soft-tissue sarcoma that can arise from patients with NF1." (PMID 33658640, 2021). "In TCGA soft tissue sarcoma project (N = 265) in cBioPortal database, patients carrying NF1 truncating or missense mutations showed significantly lower NF1 mRNA expression levels than those in non-mutated cases." (PMID 33046013, 2020). "In sporadic tumours harbouring NF1 aberrations, MEK inhibitors have been found to be effective in treating neurofibromin-deficient sporadic glioblastoma cell lines, NF1-deficient AMLs and NF1-deleted soft tissue sarcomas in mouse models." (PMID 25026295, 2014). "Aberrations of NF1 have also been reported in sporadic soft tissue sarcomas." (PMID 25026295, 2014).
Legius syndrome (35 papers, 2011 to 2025). Legius syndrome, also known as NF1-like syndrome, is a rare, genetic skin pigmentation disorder characterized by multiple cafC)-au-lait macules with or without axillary or inguinal freckling. "The need for a differential diagnosis to distinguish between CMMRD, NF1 and Legius syndrome as well as mosaic NF1 has been emphasised in the revised diagnostic criteria for NF1." (PMID 34928431, 2022). "The clinical suspicion of mosaicism justifies genetic testing for Legius syndrome and NF1, as now included in the newly formulated diagnostic criteria for the mosaic forms of both conditions." (PMID 34928431, 2022). "The most important new diagnostic criterion is the detection of a pathogenic NF1 variant, and this is especially useful in distinguishing NF1 from Legius syndrome or constitutive mismatch repair deficiency (CMMRD)." (PMID 35565289, 2022). "Previously, one more case of co-occurrence of NF1 and Legius Syndrome in the same family (with confirmed pathogenic variants in the NF1 and SPRED1 genes) was reported." (PMID 32575496, 2020). "Only one case of co-occurrence of NF1 and Legius syndrome in the same family (with confirmed pathogenic variants in the NF1 and SPRED1 genes) has previously been reported." (PMID 31443423, 2019). "As has been shown in this and previous reports Legius syndrome is associated with a milder phenotype than NF1." (PMID 21089071, 2011). "The revised diagnostic criteria for NF1, together with the newly formulated diagnostic criteria for Legius syndrome which include genetic testing for pathogenic variants in SPRED1, promise to facilitate the differential diagnosis of both disorders at an early age." (PMID 34928431, 2022). "However, the structural details of the SPRED1-NF1 complex and the effects of the pathogenic mutations observed in Legius syndrome on SPRED1’s interaction with NF1 remain to be clarified." (PMID 32697994, 2020). "This elucidates the similarity of Legius syndrome to NF1 and the mechanism by which SPREDs inhibit the Ras-ERK pathway." (PMID 39510187, 2024). "We and others have identified mutations in the EVH1 domain associated with Legius syndrome, as well as mutations in the GRD of NF1 patients that decrease the binding affinity between the GRD and the EVH1 domain." (PMID 39510187, 2024). "Legius syndrome has previously been characterized as NF1 but it is characterized by a milder phenotype compared to NF1, including freckling, macrocephaly, as well as learning impairments and attention problems." (PMID 34828352, 2021). "Because of the overlapping phenotype of Legius Syndrome with NF1, the SPRED1 gene was included in our panel." (PMID 32575496, 2020). "Recently the co-occurrence of pathogenic variants in the NF1 and SPRED1 genes was observed using NGS in one family with NF1 and Legius Syndrome." (PMID 32575496, 2020). "The Legius syndrome patient mutations SPRED1(W31C) and (T102R) are unable to inhibit cell proliferation, presumably because they fail to bind NF1." (PMID 32697994, 2020). "The ability of three functionally overlapping SPRED proteins to bind NF1 is likely responsible for the relatively benign phenotype of Legius syndrome." (PMID 32697994, 2020). "Clinically related to NF1 mutations, heterozygous variants in the SPRED1 gene, encoding another negative regulator of RAS–MAPK signaling, were reported in Legius syndrome, an autosomal dominant disorder that shows some similarities to NF1 but is less severe." (PMID 31487937, 2019). "Here, we report the co-occurrence of pathogenic variants in the NF1 and SPRED1 genes in six families with NF1 and Legius syndrome, using next-generation sequencing." (PMID 31443423, 2019). "Studies of several mouse models of RASophaties, including NF1, NS, and Legius syndrome, have demonstrated that dysregulation of the RAS-ERK pathway causes behavioral and learning deficits, altered synaptic plasticity, and structural brain abnormalities." (PMID 28455524, 2017).
Legius syndrome (continued). "Furthermore, as the authors of the revised criteria admit, patients with the much rarer Legius syndrome, caused by a pathogenic variant in the SPRED1 gene, meet these criteria for NF1 as well." (PMID 38581124, 2024). "In addition, the identification of genetic disorders with phenotypes overlapping those of NF1 has raised debate on diagnostic classification (e.g., segmental/mosaic NF1, constitutional mismatch repair deficiency (CMMRD) syndrome, Legius syndrome)." (PMID 37686284, 2023). "Legius syndrome is important for the differential diagnosis of NF1." (PMID 34449562, 2021). "Legius syndrome is a rare autosomal dominant disorder caused by heterozygous mutations in SPRED1, which negatively regulates activation of BRAF and CRAF and recruits NF1." (PMID 34828352, 2021). "In a study of 71 patients younger than 20 years of age with six or more CALMs and no other criterion, 66.2% were discovered to have NF1, 8.5% had Legius syndrome and 25.3% harbored no disease causing variant." (PMID 32014052, 2020). "Although rarer, cardiac issues may also be seen in NF1 and Legius syndrome." (PMID 35103797, 2022). "In addition to the clinical overlap between NF1 and Legius syndrome, at the biochemical level the SPRED1 protein interacts with neurofibromin, recruiting neurofibromin to the membrane and enabling Ras-GAP activity of neurofibromin and suppression of downstream ERK activation." (PMID 34311771, 2021). "Furthermore, the phenotypic overlap with NF1 and Legius syndrome has led to the acknowledgment of CMMRD as a legitimate, but presumably rare, differential diagnosis in children without malignancy who are suspected of these syndromes but lack the causative NF1 or SPRED1 variants." (PMID 30740824, 2019). "Some genetic conditions have phenotypic overlap with NF1 (e.g., Legius syndrome), and there was no clinical corroboration of participants' diagnoses." (PMID 40361300, 2025). "In contrast to NF1, frequent surveillance for tumours is not necessary in children and adults with Legius syndrome." (PMID 34928431, 2022). "For the differential diagnosis of Legius syndrome, SPRED1 vLAS was added for the patients with no identified NF1 mutations (NF_09, 13, 14, 15, and 18) and for the patients with missense variants of undetermined pathological significance (NF_10, 11, and 12)." (PMID 34449562, 2021). "SPRED1 Legius syndrome patient mutants W31C and T102R that fail to bind NF1 did not affect proliferation." (PMID 32697994, 2020). "As a rare differential diagnosis, CMMRD testing may also be indicated in children without cancer who are suspected to have sporadic NF1 or Legius syndrome but in whom no germline NF1 or SPRED1 PV has been identified by comprehensive testing." (PMID 39420201, 2024). "However, these dermatological manifestations are not exclusive to NF1; for instance, Legius syndrome (MIM: 611431) also prominently features CALMs, although with distinct molecular pathogenesis involving pathogenic variants in the SPRED1 gene (MIM: 609291)." (PMID 39001468, 2024). "In the case of eight genetically NF1 negative patients with CALMs (P29–33 and P38–40) additional Sprouty Related EVH1 Domain Containing 1 gene (SPRED1) analysis excluded the presence of Legius syndrome as well." (PMID 34325699, 2021).